C4orf54 (chromosome 4 open reading frame 54)
Synonyms: FOPV; LOC285556
Tractability: PROTAC: ubiquitination databases record sites on it.
Gene: Protein-coding gene on chromosome 4 (99,636,529 to 99,657,828, reverse strand). Ensembl gene ENSG00000248713.
Subcellular location (Human Protein Atlas): Nuclear bodies; Cytosol
Genetic constraint (gnomAD): Loss-of-function variants: 62 observed, 74.74 expected, observed/expected ratio (o/e) 0.83, 90% interval 0.68 to 1.02. The upper end of that interval is the gene's LOEUF score, 1.02, which puts it in group 4 of 6, group 1 being the genes least tolerant of losing a copy. Missense variants: 2,313 observed, 2,227.8 expected, observed/expected ratio (o/e) 1.04, 90% interval 1 to 1.07. Synonymous variants: 943 observed, 912.66 expected, observed/expected ratio (o/e) 1.03, 90% interval 0.98 to 1.09.
Homologues: Orthologues: chimpanzee C4h4orf54 (99% identical), macaque C5H4orf54 (97% identical), rabbit C4orf54 (83% identical), rat C2h4orf54 (82% identical), mouse 1110002E22Rik (82% identical), pig C4orf54 (81% identical), dog C4orf54 (78% identical), tropical clawed frog c1h4orf54 (35% identical), zebrafish C7H4orf54 (29% identical).
Diseases named in the same sentence as C4orf54 in open-access papers:
C4orf54 is named in the same sentence as 3 diseases in open-access papers, as found by Europe PMC text mining. Sharing a sentence is not in itself a finding about the gene and the disease. The quoted sentences say what the papers report.
colorectal cancer (1 paper, 2025). A primary or metastatic malignant neoplasm that affects the colon or rectum. "We used whole genome sequencing to capture information on gene targets that have mutations in the genomes of colorectal cancer and adjacent cancers and analyzed and screened high-frequency mutated genes (ATAD3B) and susceptibility genes (SH3BP1, C4orf54)." (PMID 40688112, 2025).
inflammatory breast carcinoma (1 paper, 2025). An advanced, invasive breast adenocarcinoma characterized by the presence of distinct changes in the overlying skin. "As for C4orf54, it has only been found to be downregulated in recurrent inflammatory breast cancer and may be associated with obstructive portal vein disease." (PMID 40688112, 2025).
cancer (1 paper, 2025). A tumor composed of atypical neoplastic, often pleomorphic cells that invade other tissues. "Take into account this, we roughly concluded that the more ideal cancer susceptibility genes are SH3BP1 and C4orf54." (PMID 40688112, 2025). "The probability of these six genes to be mutated in normal tissue adjacent to cancer is CPA6 (3.85%), ZNF888 (46.15%), SH3BP1 (76.92%), ANKRD16 (30.77%), ATN1 (11.54%), and C4orf54 (80.77%)." (PMID 40688112, 2025).